INS (insulin)
Diseases named in the same sentence as INS in open-access papers (continued):
Sharing a sentence is not in itself a finding about the gene and the disease.
basal cell carcinoma (6 papers, 2012 to 2024). A carcinoma involving the basal cells. "In male skin biopsies significantly up-regulated Kegg pathways were f.e. the arginine and proline metabolism, insulin signalling and acute myeloid leucemia, whereas downregulated were melanogenesis, gap junction, ubiquitin-mediated proteolysis, basal cell carcinoma and WNT signalling pathway." (PMID 23226273, 2012).
beta-cell tumors (6 papers, 2009 to 2025). "These tumors progress through a dependable course characterized by the development of insulin-secreting beta-cell tumors, leading to a gradual decrease in blood glucose until symptomatic hypoglycemic levels are reached at ~12 to 14 weeks of age30–34." (PMID 30405106, 2018). "A third approach was to derivate beta cell lines from beta cell tumours derived from transgenic mice expressing SV40T antigen under the control of the insulin promoter." (PMID 19266046, 2009). "However, it is conceivable that without appropriate control mechanisms and a degree of autonomy, an insulin-secreting beta cell tumor could develop." (PMID 34583764, 2021).
breast adenocarcinoma (6 papers, 2014 to 2025). "Another study found that Sam68 has an important role in the metabolism of hormones insulin and leptin, as its role appears in the signal transduction pathways of these hormones in three different directions for breast adenocarcinoma cells." (PMID 37900073, 2023). "The human mammary adenocarcinoma cell line MCF-7 was cultivated in DMEM with 0.01 mg/mL human insulin and 10% FBS." (PMID 33833336, 2021). "We aimed to study the expression of Sam68 and its phosphorylation level upon insulin and leptin stimulation, and the role of Sam68 in the proliferative effect and signalling pathways that are activated by insulin or leptin in human breast adenocarcinoma cells." (PMID 27415018, 2016). "Our in silico analysis identified the cyclin-dependent kinase inhibitor 1a (CDKN1A, also known as p21) as a gene of future interest, as it links the gene panels of “ROS”, “insulin resistance” and “mammary adenocarcinoma”." (PMID 24955840, 2014). "Interestingly, CDKN1A was computed to be an important nexus gene between the panels “insulin resistance” - “ROS” - “mammary adenocarcinoma”, with an induced expression at day 21 and day 28 (2.3-fold, p<0.00001)." (PMID 24955840, 2014). "In the human breast adenocarcinoma cell lines MCF7, MDA-MB-231 and BT-474, Sam68 protein quantity and gene expression were increased upon leptin or insulin stimulation, as it was checked by qPCR and immunoblot." (PMID 27415018, 2016).
cerebral oedema (6 papers, 2010 to 2025). "Given the social background, he was unable to receive insulin injections because of cerebral palsy and mental retardation." (PMID 39256230, 2024).
chronic hepatitis (6 papers, 2004 to 2024). An active inflammatory process affecting the liver for more than six months. "Our data, which show the importance of insulin resistance against HCC development, have clinically useful implications for the management of chronic hepatitis by physicians." (PMID 26913058, 2016).
chronic hepatitis B (6 papers, 2013 to 2024). "This study sought to determine whether chronic hepatitis B or C would modify the association between insulin analogues and hepatocellular carcinoma (HCC) risks." (PMID 31200528, 2019). "Except for the results obtained from normal and CHB+HS groups, another noticeable observation of the present study lied in that PNPLA3 rs1010023 did not associate with the levels of TG, insulin, FBG, and HOMA-IR in chronic hepatitis B patients." (PMID 28695131, 2017).
coagulation disorders (6 papers, 2009 to 2024). "This suggests the possibility of an association among insulin treatment, heart injury, and coagulation disorders." (PMID 38755442, 2024). "However, if the absence of a previous diagnosis of coagulation disorders was verified, or if that the patient received another type of injection in the abdomen (e.g., insulin) or anticoagulant or antiaggregant treatment." (PMID 37218948, 2023).
congenital adrenal hyperplasia (6 papers, 2012 to 2023). Congenital adrenal hyperplasia (CAH) is an inherited endocrine disorder caused by a steroidogenic enzyme deficiency that is characterized by adrenal insufficiency and variable degrees of hyper or hypo androgyny manifestations, depending of the type and the severity of the disease. "For example, nonclassical congenital adrenal hyperplasia (prior to glucocorticoid replacement) is associated with decreased insulin sensitivity as is androgen use by healthy women." (PMID 33901270, 2021). "In addition, they reported significant improvement of insulin sensitivity after adrenalectomy but not after medical treatment of bilateral adrenal hyperplasia." (PMID 22804097, 2012).
cytomegalovirus infection (6 papers, 2004 to 2025). A herpesvirus infection caused by Cytomegalovirus. "An additional reovirus resistant-clone with an insert in the Anxa2 (annexin 2) gene, associated with cytomegalovirus infection and recognized to bind to the insulin and insulin growth factor receptor-1, also failed to grow in soft agar." (PMID 15333144, 2004). "After his second transplant, he remained insulin-free for 9 months, but his GADA titers remained stably low and persisted without elevation even when he gradually lost his islet graft following an acute cytomegalovirus infection." (PMID 34205321, 2021). "Activation of AMPK induces GLUT4 expression, and HCMV infection has been shown to activate GLUT4 independently of its normal control mechanisms, which include external glucose concentration, ATP-citrate lyase (ACL) activation, insulin stimulation, and Akt activity." (PMID 23935494, 2013).
dental caries (6 papers, 2018 to 2024). The decay of a tooth, in which it becomes softened, discolored, and/or porous. "In particular, advanced glycated end products of DM2 interfere with the signaling systems activated by insulin and IGFs, leading to altered growth and turnover of dental/alveolar cells, which also occurs in the course of dental caries." (PMID 39144484, 2024). "Consistently, we found a correlation between IR and the number of dental caries, a mitogenic effect of MYO on surrogates of dental cells such as endothelial cells and fibroblasts, and informatic evidence that these two results were causally linked through insulin signaling." (PMID 39144484, 2024). "Indeed, they represent the largest pulpar cell populations; both have very similar molecular signatures in pulp and periodontium, including alveolar bone, and they respond to insulin and insulin-growth factors (IGFs) through the same receptor, which also occurs in the course of dental caries." (PMID 39144484, 2024).
energy metabolism disorders (6 papers, 2018 to 2023). "It is believed that energy metabolism disorder, insulin resistance and angiotensin activity are the main factors directly affecting cardiomyocytes caused by elevated blood glucose." (PMID 36627647, 2023). "In these two stages, the use of insulin signaling pathway drugs to treat the energy metabolism disorder and slow down the development of IR can effectively prevent the development of HF to the next stage." (PMID 35308248, 2022). "According to our results, we speculate that upregulation of FGF21 and ANGPTL4 due to NEB could diminish adipose tissue insulin sensitivity and further aggravate lipolysis during early lactation in dairy cows, thus playing a role in the pathological processes of energy metabolism disorders." (PMID 30103741, 2018). "Insulin signaling pathway is closely related to glucose metabolism, and TCM induces GLUTs expression through insulin signaling pathway, alleviates the accumulation of toxic substances induced by energy metabolism disorders, and protects neurotransmitters." (PMID 36213283, 2022).
eosinophilia (6 papers, 2010 to 2020). "Allergic reaction to insulin is known to be associated with eosinophilia and hyper IgE." (PMID 20699002, 2010). "Interestingly, 15.53 μmol/mL of insulin was partially able to restore the eosinophilia in trophozoites treated with 100 μg/mL of metformin." (PMID 32678116, 2020). "The cause of the preceding fever in this patient was not known, but this event was not the cause of the eosinophilia because the count was normal before insulin was given." (PMID 20699002, 2010). "Treatment with a single dose of insulin restored eosinophilia parameters in the blood of the animals, but not in BALF, suggesting that 8 h was insufficient time for eosinophil migration to the tissue; however, with multiple doses of insulin, we observed eosinophilia in BALF." (PMID 28649241, 2017).
frontotemporal dementia (6 papers, 2019 to 2025). Frontotemporal dementia (FTD) comprises a group of neurodegenerative disorders, characterized by progressive changes in behavior, executive dysfunction and language impairment, as a result of degeneration of the medial prefrontal and frontoinsular cortices. "However, our understanding of insulin’s role in frontotemporal lobar degeneration (FTLD) and its underlying biochemical mechanisms remains limited." (PMID 41444683, 2025). "A clinical trial (NCT04115384) evaluating the efficacy of intranasal insulin in frontotemporal dementia was suspended due to the COVID-19 pandemic." (PMID 37511207, 2023). "Here, we sought to investigate the role of central vs peripheral insulin signalling and ER stress pathways in a murine knock-in model of frontotemporal dementia (FTD), termed PLB2TAU." (PMID 31396860, 2020). "The same research group has registered a clinical trial for IN Insulin in Frontotemporal Dementia (FTD) in 12 patients, which is critical, as no treatment medicines for the advancing cognitive symptoms of FTD have been developed." (PMID 36145618, 2022).
fungal infections (6 papers, 2013 to 2024). "The patient was promptly treated with insulin in order to control the elevated HbA1c and amphotericin B to stop the fungal infection and underwent extensive surgical excision." (PMID 39618758, 2024). "However, there are still few studies relating insulin to the chronic pattern of inflammation observed in some fungal infections." (PMID 33312173, 2020). "The data presented here suggest that insulin modulates inflammatory parameters in the systemic mycosis Pb18 model in diabetic and nondiabetic mice." (PMID 30426021, 2018).
G6PD deficiency (6 papers, 2020 to 2025). An X-linked genetic condition caused by alterations in the gene G6PD that result in moderately to severely decreased activity levels of the enzyme glucose-6-phosphate dehydrogenase. "In this context, it should be recalled that G-6PD deficiency in patients is reportedly associated with impaired insulin secretion." (PMID 39854399, 2025). "The positive effect of G6PD deficiency on GLUT4 expression indicates its potential role in insulin signaling." (PMID 35806430, 2022). "G6PD deficiency impacts insulin signaling activation, while LEPR and KRAS modulate insulin sensitivity and glucose metabolism." (PMID 39823117, 2025).
gastric adenocarcinoma (6 papers, 2009 to 2024). "Proliferative effects of insulin on gastric adenocarcinoma cells were compared to those of IGF-1 and IGF-2." (PMID 34554347, 2022). "Insulin-dependent signal transduction, growth, apoptosis and anoikis were analysed in metastatic cells from gastric adenocarcinoma patients and in cell lines." (PMID 34554347, 2022). "The relative EC50 insulin concentrations in gastric adenocarcinoma cells were 1.2–15 ng/ml (0.2–2.6 nM)." (PMID 34554347, 2022). "The rarity of INS expression in gastric adenocarcinoma led us to investigate its expression in other adult cancers, twenty three with comparator normal tissue and nine without (data not shown)." (PMID 34554347, 2022). "Incubation of gastric adenocarcinoma cells with different insulin, IGF-1 or IGF-2 concentrations prior to induction of apoptosis demonstrated concentration-dependent protection." (PMID 34554347, 2022). "Objectives were to investigate if insulin promotes directly gastric adenocarcinoma cell proliferation or survival, and to explore the relative importance of the insulin receptor." (PMID 34554347, 2022). "The INSR and IGF1R genes, which encode the insulin and type I IGF receptors, were expressed in all gastric adenocarcinomas; median relative mRNA abundances were around 10 to 12 (log2)." (PMID 34554347, 2022). "High plasma insulin concentrations may promote, and increase mortality from, gastric adenocarcinoma." (PMID 34554347, 2022). "Relative mRNA abundance analysis demonstrated that INS, which encodes insulin, is not expressed in the majority, and weakly in a tiny minority, of gastric adenocarcinomas." (PMID 34554347, 2022). "This is the first report of direct effects of insulin on gastric adenocarcinoma cells." (PMID 34554347, 2022). "On the other hand, hypergastrinemia in insulin-gastrin (InsGas) transgenic mice causes gastric adenocarcinoma which is not accompanied by hyperplasia of ECL cells." (PMID 28980157, 2018). "The importance of the insulin and IGF signal transduction pathway was tested with BMS-754807 a specific dual inhibitor of the insulin and type I IGF receptors in gastric adenocarcinoma cells exposed to growth factors present in untreated FCS." (PMID 34554347, 2022). "Pharmacological inhibition of the insulin and type I IGF receptors prevented serum-stimulated gastric adenocarcinoma cell division." (PMID 34554347, 2022). "INS, IGF1 and IGF2 mRNAs were measured in a separate cohort of 1065 gastric adenocarcinomas by microarray hybridisation." (PMID 34554347, 2022). "Gastrin over-expressed in an insulin-gastrin transgenic mouse model (INSGAS) induces corpus atrophy in those mice, spontaneously progressing to gastric adenocarcinoma with advanced age." (PMID 19270747, 2009). "INS was not expressed in most gastric adenocarcinomas, or in the majority of other adult cancers types." (PMID 34554347, 2022). "The insulin and IGF signal transduction pathway is dominant in gastric adenocarcinoma." (PMID 34554347, 2022).
gastroenteritis (6 papers, 2017 to 2022). An inflammatory disorder that affects the upper and lower gastrointestinal tract. "Predisposing factors for canagliflozin-associated DKA include T1DM, concurrent insulin therapy, and an inciting illness such as gastroenteritis." (PMID 29978156, 2017). "Causal factors were identified in 40.4% of patients with syncope as follows: infection, gastroenteritis, postoperative state, rapid change of position, gastric bleeding, wrong insulin dose, and constipation with an increased effort to evacuate." (PMID 33594860, 2021). "Age < 5 years old, non-adherence, inappropriate insulin placement at home, preceding gastroenteritis, and presence of upper respiratory tract infections at the time of diabetic ketoacidosis development were significant predictors." (PMID 33143741, 2020).
haemochromatosis (6 papers, 2010 to 2025). "The impaired glucose tolerance in hereditary hemochromatosis is associated with decreased insulin secretion capacity." (PMID 40871742, 2025). "In an animal model of haemochromatosis, iron excess and oxidative stress mediate apoptosis of pancreatic islets with a resultant decrease in insulin secretory capacity." (PMID 29164513, 2018).
hemophilia (6 papers, 2007 to 2022). Hemophilia is a genetic disorder characterized by spontaneous hemorrhage or prolonged bleeding due to factor VIII or IX deficiency. "As one possible reason, the claims code of insulin needles is used not only for T1D patients, but the same claims code is used for injector needles for hemophilia patients." (PMID 33573645, 2021). "With increasing numbers of home medical treatment, e.g. insulin therapy, home dialysis and prophylactic injections for haemophilia, NSIs in the community are becoming more widely reported." (PMID 31697746, 2019). "We have demonstrated that the vector used for haemophilia therapy can be successfully modified to express insulin, and can restore euglycaemia in immunocompromised chemically induced diabetic mice." (PMID 30514969, 2019).
Hypercalciuria (6 papers, 2013 to 2025). "Additionally, hypercalciuria was overcome by treatment with insulin, again highlighting a decisive role of glucose-mediated perturbations in cellular Ca2+ homeostasis." (PMID 41244562, 2025).
hyperopia (6 papers, 2012 to 2023). A refractive error in which rays of light entering the eye parallel to the optic axis are brought to a focus behind the retina, as a result of the eyeball being too short from front to back. "Insulin injections block hyperopia and induce axial myopia in chicks most likely because of its influence on the optics of the anterior segment of eye102." (PMID 30858441, 2019). "Hyperopia (35% O2) reverses gluco-toxicity β-cell dysfunction and improves insulin secretion in the INS-1E cell line." (PMID 28179377, 2017). "Experiments performed in chickens revealed that intravitreal insulin injection inhibited choroid thickening, elongated the anterior chamber, and thickened the lens, accelerating lens-induced axial myopia and inhibiting lens-induced hyperopia." (PMID 36593443, 2023).
hypertrichosis (6 papers, 2016 to 2025). Excessive hair growth anywhere on the body. "Intermittent exacerbations and failure to effectively control laminitis pain contributed to a decision for euthanasia in five horses, four of which had advanced signs of PPID (hypertrichosis scores of 3) and all five had increased serum insulin concentrations at the start of the study." (PMID 40317948, 2025). "Significant contributors to laminitis risk included a higher body condition score, evidence of divergent hoof growth, the presence of hypertrichosis on veterinary examination, increasing age, higher [insulin]T0 and [insulin]T60, lower [adiponectin] and lower exercise levels and/or intensity." (PMID 35263471, 2023).
ischemic cardiomyopathy (6 papers, 2020 to 2025). Ischemic cardiomyopathy is a cardiomyopathy in which a weakness in the muscle of the heart due to inadequate oxygen delivery to the myocardium with coronary artery disease being the most common cause. "In patients with established ischemic cardiomyopathy, reduced insulin activity limits glucose utilization by cardiomyocytes, forcing a shift to fatty acid metabolism." (PMID 40255500, 2025). "Additionally, in patients with diagnosed ischemic cardiomyopathy, reduced insulin activity may limit glucose bioavailability, leading to a metabolic shift toward fatty acid oxidation." (PMID 40700433, 2025).
Lipoatrophy (6 papers, 2009 to 2025). Localized loss of fat tissue. "Based on our case presentation and review of the literature, the following diagnostic and management algorithm is proposed for patients with insulin pump–induced lipoatrophy." (PMID 40746499, 2025). "With insulin analog injections/infusions, the prevalence of lipoatrophy had been reported to be 2.5 % in a single center study and 1.1 % in a multicenter survey." (PMID 28702229, 2015). "With the availability of purer animal and human insulin, the prevalence of lipoatrophy decreased to 0.2-1.4 %." (PMID 28702229, 2015). "In conclusion, the case of our patient supports the use of prolonged low-dose corticosteroid treatment to cure progressive insulin-induced lipoatrophy." (PMID 22145998, 2011).